CD4 (CD4 molecule)
Diseases named in the same sentence as CD4 in open-access papers (continued):
Sharing a sentence is not in itself a finding about the gene and the disease.
cancer (continued). "We found that the transcriptomic factor (XBP1) was the top-ranked in both macrophages and naïve CD4 + T cells in cancer." (PMID 36221095, 2022). "LMNB1 is a biomarker of CD4+ Th2 cell infiltration and DNA homologous recombination repair in human cancers." (PMID 35241075, 2022). "Some reports suggest that tumors induce T cell senescence via cancer cell–derived soluble molecules, while other studies implicate CD4+ regulatory T cells in this process." (PMID 36099049, 2022). "Cancer vaccines use tumour associated antigens to stimulate CD4+ and CD8+ T cells, inducing the immune system of the patient to target cancer cells that were previously successfully evading immune suppression." (PMID 36003779, 2022). "The results indicated that patients with a high-risk score were in an immune “cold” phenotypic state, with low levels of immune cell infiltration (e.g., CD4+) and cancer-immunity cycle steps as well as reduced antigen-presenting capacity (e.g., aDCs)." (PMID 36386203, 2022). "For example, P-gp in exosomes was reportedly elevated in doxorubicin-resistant PCa, while another study showed that it enhanced the anti-cancer ability of anti-cancer cytokines, such as CD4+ T cells, in ovarian cancer." (PMID 35747825, 2022). "The incubation of activated CD4+ T cells with cancer supernatants reduced the PI3K, NFκB, and JAK-STAT3 pathway activities and increased the TGFβ pathway activity, characteristic of an immunotolerant state." (PMID 35158758, 2022). "CD8+ and CD4+ T-cells play a key role in cellular immune responses against cancer by cytotoxic responses and effector lineages differentiation, respectively." (PMID 36232369, 2022). "Taken together, we concluded that cancers generate B-MF mostly to downregulate anticancer IFNγ+CD4+ T cells." (PMID 36104343, 2022). "Mature DCs are then infused back into patients wherein they will present the cancer antigens to CD4+ and CD8+ T cells." (PMID 35804943, 2022). "It is a potent regulator of immunity and cancer development because it promotes the differentiation of naïve CD4+ T cells into the CD4+ Th2 subset and can also influence the function of mature CD8+ T cells." (PMID 36552602, 2022). "CD47 expression was positively associated with CD4+ T cell, CD8+ T cell, B cell, neutrophil, dendritic cell, and macrophage infiltration of numerous cancers." (PMID 35697717, 2022). "Herein, UNC5A expression was found to be significantly related to CD8+ T cells in 9 cancers, B cells in 10 diverse cancer types, CD4+ T cells in 21 cancers, macrophages in 16 cancers, neutrophils in 18 cancer types, and dendritic cells in 18 cancer types." (PMID 36551254, 2022). "In contrast, many studies have confirmed that the percentage and absolute number of CD4+ CD25+ T cells increased in the peripheral circulation of patients diagnosed with malignant neoplasms." (PMID 35158748, 2022). "Significant reduction of the rates of these cancers by cART is believed to be due to ameliorating the suppressed immune responses, including depletion of CD4+ T helper cells, exhaustion of lymphopoiesis, and so forth." (PMID 35453518, 2022). "ALKBH7 expression displayed a strong relationship with dendritic cells in 8 cancer types, macrophages in 9 cancer types, neutrophils in 11 cancer types, CD8+ T cells in 14 cancer types, B cells in 8 cancer types and CD4+ T cells in 3 cancer types." (PMID 35222541, 2022). "We identified, in the blood of cancer patients, a population of CD4 T cells expressing inhibitory receptors targeted by immunotherapy." (PMID 35954341, 2022). "We recently reported that another NK-cell-associated molecule, signalling lymphocyte activation molecule family member 7 (SLAMF7), is enriched in CD4 CTLs in cancer patients." (PMID 35572552, 2022). "The fraction of naive B cells, resting T cells CD4 memory, T cells follicular helper, γδ T cells, resting mast cells, and M2 macrophages was higher in normal adjacent tissue than in cancer tissue." (PMID 35646079, 2022).
cancer (continued). "CD4 T-cell responses are essential in the cancer immune cycle and substantially influence the clinical outcome." (PMID 36139524, 2022). "For the immune cell types among cancers, we revealed that m7Gscore had inverse correlation with most immune cells, except for activated CD4 T cell, memory B cell and Th2 cell." (PMID 36339001, 2022). "After Denosumab treatment, total T cells isolated from cancer patient were reduced from 14.51 ± 3.71% to 3.88 ± 1.77% and CD4+CFSE− cell reduced from 5.32 ± 0.76% to 1.33 ± 2.31%." (PMID 36097003, 2022). "A recent study has found that CD4 T cells representing an alternative/synergistic population to classical CD8 T cells and the cytolytic activity of CD4 T cells against tumors requires MHC-II expression in cancer cells." (PMID 35223828, 2022). "There were different opinions on the effect of CD4+ CD25+ regulatory T cells on the prognosis of cancer patients." (PMID 35047040, 2022). "The results showed that ACSL4 expression was significantly associated with NK, B cells, macrophages, DC, CD4+ T cells, CD8+ T cells, monocytes and neutrophil infiltration in 13, 16, 19, 24, 25, 26, 28 and 31 cancer types." (PMID 35126480, 2022). "To further validate those results, we also analyzed the immune cell composition among cancers using TCIA database and we also observed that only CD4 T cell was positively correlated with m7Gscore in most cancers." (PMID 36339001, 2022). "Coculturing CD4+ T cells with CD8+ T cells increased migration of CD8+ T cells towards the cancer cells approximately ten-fold when compared with CD8+ T cell monoculture." (PMID 35359980, 2022). "Thereby, the importance of CD4+ T-cells in senescence and cancer surveillance in context of cancer immunosurveillance is supported in the current study samples." (PMID 36157879, 2022). "CD4 + T cell subsets, such as Th1, Th2, Th17, and regulatory T (Treg) cells, play a crucial role in cancer immunity." (PMID 35790819, 2022). "In comparing normal to cancer tissue, CD8 T cells was the only feature, on average, increased in cancer tissue, while CD4 T cells and CAFs were decreased and active NK cells, B cells, and Macrophages exhibited similar trends." (PMID 35418177, 2022). "First, we selected the target genes of the top regulon from macrophages (cancer) and naïve CD4 + T cells (cancer), respectively, and visualized them in network." (PMID 36221095, 2022). "The enrichment of PD-1+CD39+ CD4 T cells in cancer patients was evocative of their involvement in an ongoing immune response." (PMID 35954341, 2022). "Lower CD4 cell counts at the time of ART initiation and older age were associated with higher risk of developing cancer." (PMID 34873875, 2022). "The result of the ssGSEA algorithm showed that the expression of B cells, CD4+ Th2 cells, CD4+ naïve T cells, CD8+ central memory T cells, cancer-associated fibroblasts, and macrophages were significantly higher." (PMID 36134026, 2022). "It has also been illustrated that CD4+ CTLA-4+ T cells in circulation are considerably elevated in patients with advanced cancer stages." (PMID 35855850, 2022). "These CD4+ T cells with cytotoxic functions have been found in certain viral infections, autoimmune disorders and cancer." (PMID 35008422, 2022). "T cells can recognize and kill cancer cells, and CD4+ T conventional (Tconv) cells are the main orchestrators of cancer immune function." (PMID 35603183, 2022). "As CTLA-4 is a marker of T cell activation, its elevated expression indicates increased CD4+ T cell activation in the TME of these cancers." (PMID 36497170, 2022). "Tfr cells, generally defined as CXCR5+FOXP3+BCL6±ICOS± CD4+ cells, have been detected intratumorally in various cancers with limited assessments of their prognostic value." (PMID 36077836, 2022). "Due to these clinical findings indicating that CD4+ T-cell-mediated antitumor immunity is indispensable for cancer immunotherapy, MHC-II-epitope predictors have been recently improved." (PMID 35456701, 2022).
cancer (continued). "Various subsets of CD4+ T cells play multifaceted roles in the cancer response, including Th2, and Th17." (PMID 35783272, 2022). "CD4+ T cell activation in infectious diseases and cancer is governed by the recognition of peptides presented on class II human leukocyte antigen (HLA-II) molecules." (PMID 35494241, 2022). "EZH2 expression revealed a positive relationship with infiltrating levels of CD8 + T cells in 20 cancer cases, those of macrophages for 12 cancers, those of CD4 + T cells for 18 cancers, those of DCs for 19 cancers, and those of neutrophils for 24 cancers." (PMID 35659256, 2022). "TH9 cells have emerged as a unique CD4 T-cell subset of particular interest for adoptive cell therapy of cancer." (PMID 35091453, 2022). "Cancer cells and CD4+ T cells show metabolic coupling, and the coupling is mediated by TGF-β signaling." (PMID 36115986, 2022). "In most cancer types, NUTF2 expression was positively associated with infiltrated activated CD8+ T cell, central memory CD4+ T cell, gamma delta T cell, CD56bright/CD56dim NK cell and monocyte." (PMID 35155261, 2022). "In our research, we discovered that DTYMK was able to reliably activate all six different kinds of immune cells (neutrophils, CD8+ T cells, macrophages, dendritic cells, CD4+ T cells, and B cells) in most kinds of cancer, except in BLCA and CHOL." (PMID 36094557, 2022). "MHC I and MHC II can be recognized by cytotoxic CD8+ T cells and CD4+ helper T cells, respectively, and consequently trigger immune responses such as anticancer immunity during cancer progression." (PMID 35454945, 2022). "Further analysis revealed that miR-942 expression was significantly correlated with several types of immune cell infiltration, including stroma score, CD4 T helper 1 cell, CD4 T helper 2 cell, CD8 T cell and cancer associated fibroblast." (PMID 36581942, 2022). "For example, SLC2A1 was significantly postively correlated with Th2 CD4+ T cells and significantly negtively correlated with CD 8 + T cell, M2 macrophages and B cell in a variety of cancers." (PMID 36712872, 2022). "Compared with ACSL4 wild type, ACSL4 mutation caused significant changes in CD4+ T cells, DC, macrophages and CAF, and showed opposite trends in both types of cancer." (PMID 35126480, 2022). "Altogether, these observations are in line with our previous study demonstrating that MSC-IPr-induced anti-tumoral immunity requires both CD8 and CD4 T cells (mostly likely participating in antibody production) to protect the host from cancer growth." (PMID 35203247, 2022). "To summarize, the presence of human CD4+ T cells capable of killing cancer cells via perforin and granzyme B pathways has been established by several independent studies." (PMID 36159781, 2022). "The expression of ARPC5 was significantly associated with CD4+ T cell in 20 cancers, CD8+ T cell in 25 cancers, neutrophil cell in 32 cancers, macrophage cell in 27 cancers, and DC cell in 29 cancer types." (PMID 36148220, 2022). "The median baseline CD4 count among patients who developed cancer was lower (106 cells/mm3, IQR 54–196) than among those who did not (170 cells/mm3, IQR 84–276), p = .001." (PMID 34873875, 2022). "A vaccine containing telomerase-derived cancer peptides, UCPVax, has been designed to activate CD4+ T-helper cells against telomerase-expressing cells." (PMID 35887235, 2022). "CRNDE-h levels are upregulated in naive CD4+ T cells exposed to cancer cell-secreted exosomes, indicating the transfer of CRNDE-h into CD4+ T cells via exosomes." (PMID 35055115, 2022). "In particular, the GSVA score was negatively correlated with CD4+ T and positively correlated with neutrophil cells in a majority of cancer types." (PMID 36276096, 2022). "In this regard, the role of peripheral CD4 TL has gained considerable interest for cancer immunotherapy in the last few years." (PMID 35546670, 2022).
cancer (continued). "Compared with the adjacent tissues, the percentage of PD-1+CD4+T cells in cancer tissues was significantly increased." (PMID 35725444, 2022). "In addition, significantly more macrophage M0 and cancer-associated fibroblast infiltration was found in the high-risk group, which had significantly less NK and memory CD4 T cell infiltration that might have further exacerbated the immune depletion status of patients." (PMID 35711417, 2022). "Recently, studies using single-cell RNA sequencing (scRNAseq) have characterized antigen-specific cytotoxic CD4+ T cells in various cancers, including melanoma, breast, and colon cancer." (PMID 35831288, 2022). "We then quantified the percentage of cancer cells killed at 80 hours (CD4 T cells) or 32 hours (CD8 T cells) after each stimulation." (PMID 36350984, 2022). "Indoleamine 2,3-dioxygenase (IDO) expressed by cancer cells directly amplifies Treg cells by transforming CD4+CD25-T cells to CD4+CD25+ Treg cells." (PMID 36569832, 2022). "TMB, MSI, MMR, DNA methylation, and RNA modification played a significant role in mediating MPZL3 dysregulation in cancers, and MPZL3 was closely linked to CD8+ T cells and CD4+ T immune infiltration." (PMID 35965540, 2022). "Once activated, T-cells (either CD4+ or CD8+) are crucial in achieving an anti-cancer immune response by effector and memory cells." (PMID 36224614, 2022). "In this setting, in vitro data suggest that the proliferation of cancer cells harboring CCL5 receptors is related to CD4 T cells, which are the main CCL5 producers among other immune cells." (PMID 36429101, 2022). "The dysfunction of Wnt signaling pathway is associated with the progression of many cancers, and promotes immunosuppression in TME by regulating the differentiation and maturation of CD4+ Tregs and other variety of inflammatory cells." (PMID 35903696, 2022). "This present research found that XIST was related to infiltration levels of T cell CD4+, Tregs, mast cell, Th1, macrophage and T cell NK in more than 8 types of cancers." (PMID 36212008, 2022). "By suppressing the NF-κB/CCL22 axis in M2 macrophages, the fucoidan limits cancer cell mobility and reduces intratumoral CD4(+) regulatory T cells (Tregs) to enhance cancer therapeutics." (PMID 36109724, 2022). "The fraction of B cells, CD4+ T cells, CD8+ T cells, macrophages, NK cells, cancer-associated fibroblasts, and endothelial cells was predicted using the EPIC deconvolution method." (PMID 36539408, 2022). "Determining such mechanisms is of importance for cancer treatment as they will provide insight into when engaging CD4+ T cells, either alone or alongside CD8+ T cells, will mediate effective antitumor immunity." (PMID 36159781, 2022). "We have previously shown that CD4 responses to citrullinated peptides can be detected in healthy donors and cancer patients." (PMID 36544781, 2022). "Normal CD4+ T cells were more sensitive to cytotoxic compounds than cancer cells, as demonstrated by the MTT test, TUNEL assay, and the measurement of live, apoptotic, and dead cells by flow cytometry." (PMID 35163785, 2022). "Like immune inflamed cancer, C1 showed activated DC cells, M1 macrophage, activated NK cells, activated CD4+ T memory cells, CD8+ cells, and follicular T helper cells." (PMID 35223837, 2022). "NK T cells and CD4+ Th1 T cells were positively correlated with ALKBH7 gene expression in most cancers." (PMID 35222541, 2022). "We present data showing that PD-1+CD39+ CD4 T cells in circulation reflect an ongoing adaptive immune response, which, in cancer patients with HPV-induced tumors, was directed against HPV Ags and was predictive of the response to PD-1/PD-L1 axis blockade." (PMID 35954341, 2022). "It is widely acknowledged that CD4 + T cells play a prominent role in cancer immunosurveillance and immunotherapy." (PMID 36138435, 2022). "The CD4+/CD8+ ratio is a marker of cell-mediated immunity in cancer patients, and its reduction is related to a low immunological function." (PMID 35484541, 2022).
cancer (continued). "Our results also showed that lower levels of peripheral CD4+ and CD8+ T cells were associated with higher levels of CD4+and lower levels of CD8+T cells in cancer tissue." (PMID 35051220, 2022). "STAT3 expression positively correlated with the infiltration of resting memory CD4+ T and naive B cells in most tumors and negatively associated with the infiltration of TFHs, CD8+ T, activated NK, and memory B cells in different cancer types." (PMID 36176415, 2022). "We also noted lower activities of many steps in MGCS2, including release of cancer cell antigens (Step 1), cancer antigen presentation (Step 2), CD4 T cell, CD8 T cell, and Th1 cell recruiting (Step 4)." (PMID 35592316, 2022). "Current pharmacological inhibitors for Wnt-β-catenin targeting cancer stem cells can be also applied for eliminate HIV-1 infected CD4+ TSCM cells." (PMID 36059484, 2022). "Cancer immunosurveillance is promoted by therapies targeting the interaction between NETs and naïve CD4+ T cells or inhibiting Treg activity, thus preventing HCC formation." (PMID 36612251, 2022). "Overall, CD4 + T cells play a key role in regulating the cancer immune microenvironment, and our study demonstrated that KCNJ14 mainly regulates the infiltration of CD4 + and CD8 + cells to influence the development of CRC." (PMID 36100894, 2022). "The expression of RBX1 was in connection with the infiltration of B cell, CD4+ T cells and neutrophils in above four cancers." (PMID 36059474, 2022). "Dendritic cells (DCs), activated by cancer antigen, secrete IL-12, and IL-12 induces activation of naive CD4+ T cells and naive CD8+ T cells into T1 and T8 cells, respectively." (PMID 36355837, 2022). "LL-37 treatment appeared to reduce the immunosuppressive cells of MDSCs (CD11b+Gr-1+) and M2 macrophages (CD206+F4/80+) and to increase the anti-cancer effectors CD4+T (CD4+CD3+) and CD8+T (CD8+CD3+) cells." (PMID 35935871, 2022). "For instance, its expression is negatively correlated with T cell CD4 memory resting in 24 cancers and positively correlated with T_cells_regulatory_(Tregs) in 13 cancers." (PMID 36419876, 2022). "CD103+ TAMCs appeared more mature, more prone to interact with CD4+ T cells, and located closer to cancer cells than their CD103− counterpart." (PMID 35326546, 2022). "B cells (P < 0.001), T cells CD4+ naïve (P = 0.004), T cells CD8+ naïve (P = 0.031), T cells CD8+ (P = 0.015), cancer-associated fibroblasts (P < 0.001), neutrophils (P = 0.001), and B cells plasma (P = 0.001) were decreased in the high-risk group." (PMID 36452497, 2022). "CD4+ T cell activation for cancer immunoprevention and therapy has several distinct advantages compared with conventional immunotherapies directed at CD8+ T cells." (PMID 35657353, 2022). "ACKR3 is described as expressed on hematopoietic cells, neurons, mesenchymal cells, endothelial cells, and cancer cells, CD4 T lymphocytes, NK cells, dendritic cells, neutrophils, monocytes, and macrophages." (PMID 36552863, 2022). "Studies have elucidated a prominent role of CD4+ T cells in cancer vaccine clinical trials against multiple cancer types, including melanoma." (PMID 35529885, 2022). "Simultaneously, macrophages and naïve CD4 + T cells exhibit stronger interactions in cancer, which indicated that macrophage-naïve CD4 + T cell interaction essentially affects the cancerous state." (PMID 36221095, 2022). "As immunotherapy becomes a valid treatment method for cancer, CD4+ T helper cells have received extensive attention as a crucial component of immune response." (PMID 35546682, 2022). "Another interesting result in this study is that YAP1 expression was negatively correlated with infiltration of CD8+ T cells, but positively correlated with infiltration of resting CD4+ memory T cells in most cancer types." (PMID 36479120, 2022).